PDGFRB (platelet derived growth factor receptor beta)
Diseases named in the same sentence as PDGFRB in open-access papers (continued):
Sharing a sentence is not in itself a finding about the gene and the disease.
melanoma (107 papers, 2005 to 2025). A malignant, usually aggressive tumor composed of atypical, neoplastic melanocytes. "Various phenotypic and transcriptional events have been previously associated with melanoma brain metastasis, including destabilisation of tight junctions, EndMT and activation of TGFβ/PDGFβ/PDGFRβ signalling." (PMID 40654904, 2025). "In contrast, desensitisation of PLX4032-resistant melanoma to dacarbazine is caused by canonical MAPK-independent survival through IL8/PDGFRβ-dependent bypass signalling via AKT38,39." (PMID 30631106, 2019). "In our study, kinase substrates encoding for EGFR and PDGFRβ were found to be significantly differentially affected by ex-vivo vemurafenib in melanoma tumors harboring BRAF(V600E) and BRAF wild-type." (PMID 24023633, 2013). "The RTK hyperactivation in melanoma is mainly due to EGFR, PDGFRβ, and IGF1R receptor overexpression or genetic mutations constantly activating RTK." (PMID 40872623, 2025). "Upon transfer to recipient melanoma cells, PDGFRβ triggers a dose-dependent activation of the PI3K/AKT signaling pathway, enabling these cells to circumvent BRAF inhibition." (PMID 39403600, 2024). "qPCR analysis showed an increase in PDGFRβ mRNA levels in resistant melanoma cell lines with statistical significance in the WM9 R line." (PMID 39175042, 2024). "Platelet-derived growth factor receptor-beta (PDGFRβ), a critical factor in resistance, is enriched in EVs released by melanoma cells that are resistant to the BRAF inhibitor PLX4720." (PMID 39403600, 2024). "With these experiments, the authors found that small EVs released from resistant melanoma cells had more PDGFRβ expression compared to sensitive cells and proved that EV-derived PDGFRβ can also be transferred from resistant to sensitive cell lines." (PMID 36831417, 2023). "It has been shown that increased PDGFRB expression in melanoma cells makes them resistant to the BRAF inhibitor." (PMID 35565444, 2022). "For example, in melanoma, the transfer of receptor PDGFRβ by EVs from melanoma donor cells leads to an activation of the PI3K/AKT pathway on BRAF-mutated recipient cells." (PMID 34205256, 2021). "The expression of various receptor tyrosine kinases, like AXL, PDGFRB, and EGFR, in cutaneous melanoma occurs in MITFlow melanoma cells with a pro-invasive potential and has been associated with BRAF/MEK inhibitor resistance." (PMID 34360915, 2021). "The expression of various receptor tyrosine kinases, including AXL, PDGFRB, and EGFR, in cutaneous melanoma occurs in MITFlow melanoma cells with a proinvasive potential and has been associated with BRAF/MEK inhibitor resistance." (PMID 33916908, 2021). "PDGFRβ, belonging to the group of tyrosine kinase receptors, is overexpressed in melanoma and was identified as a drug resistance factor." (PMID 34575876, 2021). "Exosomes were shown to transfer PDGFRβ to melanoma cells, activating the phosphatidylinositol-3-kinase (PI3K-AKT) signaling pathway, involved in the growth and survival of cancer cells, consequently lowering the sensitivity to BRAF inhibitors." (PMID 34575876, 2021). "A375R cells were generated by continuous selective culture in vemurafenib; immunoblot-detection confirmed PDGFRβ-upregulation in these cells, an established signature molecular change characteristic of vemurafenib-resistant melanoma cells." (PMID 31035569, 2019). "We also explored possible changes in the expression of epidermal growth factor receptor (EGFR) and platelet‐derived growth factor receptor beta (PDGFRβ), since these receptors have previously been related to BRAFi resistance in melanomas." (PMID 30582770, 2019). "Among these genes, E2F2 and PDGFRB were widely recognized as key genes that impact melanoma secretion." (PMID 30214427, 2018). "Low MITF expression in melanomas has previously been linked to increased expression of RTKs such as AXL, EGFR, and PDGFRβ, which activate immediate–early signaling, causing resistance to RAF/MEK inhibitors." (PMID 28069687, 2017).
melanoma (continued). "In contrast, in ERK-independent resistance, platelet-derived growth factor receptor-β (PDGFRβ) is overexpressed in BRAFV600E inhibitor-resistant melanoma cells, leading to renewed proliferation and tumour growth." (PMID 28708099, 2017). "This conclusion is based on: 1) the down regulation of AXL, EGFR, IGF-1R and PDGFRβ in ShRUNX2 knocked down melanoma cell lines or RUNX2-specific U1 Adaptors-transfected melanoma cells." (PMID 27102439, 2016). "Several studies have shown that over-expression of EGFR, FGFR3, PDGFRβ, CRAF, and NRAS in melanoma have been associated with BRAFi resistance." (PMID 27448964, 2016). "We have demonstrated that RUNX2-deficient melanoma cells display a significant decrease in three receptor tyrosine kinases, EGFR, IGF-1R and PDGFRβ." (PMID 27102439, 2016). "AXL is expressed in 6 out of the 9 melanoma cell lines tested, and PDGFRβ is expressed at high levels in three cell lines and at lower levels or undetectable in the others." (PMID 27102439, 2016). "Upregulation of various RTKs or their ligands have been reported in MAPK-inhibitor resistant melanoma, including PDGFRβ, IGF-R1, HGF, FGFR2, NRG1 and the EGFR family (EGFR, ERBB2, ERBB3, ERBB4)." (PMID 26426052, 2015). "As we have previously reported that P-Rex1 plays a key role in melanoma progression, we screened a number of melanoma cell lines for the combined expression of P-Rex1 and PDGFRβ." (PMID 23382862, 2013). "MAPK/Erk1/2 activation via C-RAF overexpression and upregulation of RTKs (PDGFRβ and IGF-1R) or N-RAS mutation have been reported to be among the mechanisms by which melanoma cells acquire resistance to B-RAF inhibitors." (PMID 23418523, 2013). "Consistently, the invasiveness of WM852 melanoma cells, which endogenously express P-Rex1 and PDGFRβ, is opposed by siRNA of either of these proteins." (PMID 23382862, 2013). "In this way we identified the WM852 melanoma line as one which expresses detectable levels of P-Rex1 and PDGFRβ and which is amenable to gene silencing with specific siRNA oligonucleotides." (PMID 23382862, 2013). "Interestingly, our in vitro observations suggest that nintedanib's effect on melanoma cells cannot be solely explain through PDGFRβ inhibition." (PMID 35156321, 2022). "They showed that PDGFRb could be transferred via EVs from resistant melanoma cells to recipient melanoma cells, resulting in a dose-dependent activation of PI3K/AKT signaling and escape, thus resistance, from BRAF inhibition." (PMID 36289847, 2022). "Likewise, PI3K/AKT induction resulting from EV-mediated transfer of platelet-derived growth factor receptor-beta (PDGFR-β) has been shown to be responsible for melanoma resistance to the BRAF inhibitor PLX4720." (PMID 33670185, 2021). "EVs from drug-resistant melanoma cells were enriched with the RTK PDGFRβ, and delivering EVs rich in PDGFRβ to metastatic melanoma cells with the BRAF inhibitor-sensitive phenotype activated the PI3K/AKT pathway and resulted in the development of drug resistance." (PMID 34685720, 2021). "Additionally, platelet-derived growth factor receptor-beta (PDGFR-β), which is greatly increased in T-EVs discharged by melanoma cells resistant to the BRAF inhibitor PLX4720, can be transported to recipient melanoma cells." (PMID 33081785, 2020). "Moreover, PDGFRβ has been shown to mediate Vemurafenib resistance through transcriptional upregulation in melanoma." (PMID 30777101, 2019). "Because IGF-1R, FGFR1, and EGFR have been shown to play major roles in melanoma progression through autocrine signaling, and EGF-R, PDGFRβ, and IGF-1R have been implicated in resistance mechanisms to BRAF V600E targeted therapies, we were interested in validating these results." (PMID 27102439, 2016). "Nazarian and co-workers showed that melanomas harboring a BRAF (V600E) mutation eventually become resistant to the RAF-selective inhibitor, PLX4032, by activation of an alternative survival pathway mediated by PDGFRβ." (PMID 24885200, 2014).
melanoma (continued). "Moreover the authors found that 4 of 11 post-relapse biopsies from melanoma patients treated with Vemurafenib showed increased expression of PDGFRβ in comparison to pre-treatment biopsies." (PMID 23515890, 2013). "Given that expression of P-Rex1 appears to be a key determinant in formation of distant metastases in a number of models, including melanoma, breast and prostate cancer, we propose that in certain contexts PDGFRβ and P-Rex1 may act as a novel, pro-invasive signalling module." (PMID 23382862, 2013). "Moreover, in light of our recent description of P-Rex1 as a key driver of melanoma progression in vivo, it is noteworthy that a common mechanism of acquired resistance to novel therapeutic kinase inhibitors in BRAFV600E driven melanoma is upregulation of PDGFRβ." (PMID 23382862, 2013). "In particular, a study showed that the downregulation of SOX10 in melanoma activated TGFβ to induce upregulation of EGFR and PDGFRβ, which then conferred resistance to MAPK inhibition." (PMID 40872623, 2025). "The results of in vitro research point to the possibility that the PDGFRB and FOXM1 genes function as oncogenes in melanoma." (PMID 36467505, 2022). "The levels of αSMA, PDGFRβ and FAP in melanoma and pancreatic tumours were nearly undetectable in Atf4Δ/Δ mice, which indicates that ATF4 is essential for CAF activation within the TME." (PMID 35654839, 2022). "The outcomes of immunohistochemistry experiments demonstrated that PDGFRB and FOXM1 were overexpressed in melanoma samples in comparison to normal tissues." (PMID 36467505, 2022). "In melanoma cells, the expression of receptor tyrosine kinases such as EGFR, PDGFRB, and ERBB3 increases upon exposition to BRAF/MEK inhibitors." (PMID 35565444, 2022). "Based on in vitro experiments, we found that silencing PDGFRB and FOXM1 inhibited the proliferative capacity of melanoma cells." (PMID 36467505, 2022). "Studies showed that receptor tyrosine kinases (RTK) such as PDGFRβ, IGF1R, EGFR and c-Met were overexpressed in melanoma cells." (PMID 28708099, 2017). "By switching to the mesenchymal phenotype, melanoma cells gained additional “tools” to signal via PI3K, e.g. up-regulated receptor-tyrosine kinases (RTKs) like Axl and PDGFRB or ECM fibronectin." (PMID 26918352, 2016). "Up-regulation of the expression of EGF-R, PDGFRβ, AXL and IGF-1R in melanoma cells that have developed resistance to BRAF V600E targeted therapy results in reactivation of the MAPK and the PI3K/AKT pathways." (PMID 27102439, 2016). "We demonstrated the co-expression of RUNX2 with IGF-1R, EGF-R, PDGFRβ and AXL using ShRNA RUNX2-expressing melanoma cells and showed co-expression of RUNX2 with AXL in human melanoma samples." (PMID 27102439, 2016). "In response to MAPK pathway inhibition, some melanoma cells undergo transcriptional reprogramming towards a melanocytic lineage dedifferentiation cell state characterized by the expression of receptor tyrosine kinases such as AXL, PDGFRβ or NGFR." (PMID 36774337, 2023). "CAFs were isolated from a cutaneous MM biopsy and were characterized: cells showed a spindle-shape and flattened morphology, and were strongly positive for vimentin and PDGFRβ according to the literature but were negative for the melanoma marker Melan-A." (PMID 34638245, 2021). "Next, we checked whether the preincubation of A375 melanoma cells with vitamin D derivatives affected the protein level of VEGFR1, VEGFR2, PDGFRa, PDGFRb, or VDR after subsequent treatment with cediranib." (PMID 35004285, 2021). "It is worth noting that the BRAF(V600E) melanoma cell lines with a PDGFRα up-regulation mediated BRAF-I resistance did not express PDGFRβ and VEGFR2." (PMID 24732172, 2014). "IGFR1 and PDGFRβ are involved in the acquired BRAF-I resistance of melanoma." (PMID 24732172, 2014). "Indeed, we present data which demonstrates that in vitro invasive migration of a human melanoma derived cell line, WM852, is dependent upon expression of both P-Rex1 and PDGFRβ." (PMID 23382862, 2013).
melanoma (continued). "Given the critical role of RTK upregulation such as PDGFRβ and of the pro‐fibrotic TGF‐β signaling pathway overactivation in mesenchymal resistance, we stimulated MAPKi‐sensitive melanoma cells with PDGF‐BB or with TGF‐β and analyzed miR‐143‐3p and miR‐145‐5p expression." (PMID 35156321, 2022). "Other studies showed that six out of 16 melanoma tumors acquired EGFR expression after the development of resistance to BRAF or MEK inhibitors, and acquired resistance was found with the overexpression of signaling receptors like EGFR, PDGFRβ, or MET that reactivation the MAPK pathway." (PMID 34360915, 2021). "However, A375‐R melanoma cells only showed a significant increase in the expression of EGFR but not in PDGFRβ levels." (PMID 30582770, 2019). "A decrease in the activity of sex determining region Y-box 10 (SOX10) described in some melanomas may lead to signalization through TGF-β, which in turn leads to an increase in the expression of EGFR and the receptor of the platelet-derived growth factor (PDGFRB)." (PMID 32605090, 2020). "Mechanisms of drug resistance in melanoma to vemurafenib do not involve mutations in BRAF itself but are associated with a variety of molecular changes including RAF1 or COT gene over expression, activating mutations in RAS or increased activation of the receptor tyrosine kinase PDGFRβ." (PMID 25562798, 2012). "Authors also found that the development of resistance obtained through EVs carrying PDGFRβ was not just a prerogative of the cell line LM-MEL-64, but also of another melanoma cell line (M229AR) after the exposure to BRAF-inhibitors and linked to resistance." (PMID 36831417, 2023). "Reduced levels of the receptor tyrosine kinases IGF-1R, FGFR1, PDGFRβ, and EGFR were detected in the RUNX2 knocked down 1205LU melanoma cells as compared with the non-silencing (control) ShRNA-expressing 1205LU cells." (PMID 27102439, 2016).
gastrointestinal stromal tumor (80 papers, 2004 to 2026). "While inhibition of both ABL paralogs might contribute to the observed side effects of imatinib treatment, imatinib is used to target c-kit-mutated gastrointestinal stroma tumors (GIST) or PDGFRβ-mutated chronic myelomonocytic leukemia (CMML)." (PMID 34262462, 2021). "Imatinib is a tyrosine kinase inhibitor that specifically targets the kinase activity of PDGFRβ, ABL, and c-KIT and has been approved for the treatment of chronic myeloid leukemia and gastrointestinal stromal tumors (20, –, 24)." (PMID 33753340, 2021). "PDGF, a fundamental protein stored in platelet α-granules, along with its receptors (PDGFRα and PDGFRβ), is expressed in numerous malignant cells and tissues, including NSCLC, gastrointestinal stromal tumors (GIST), and pancreatic, breast, ovarian, hepatocellular, and neuroendocrine cancers." (PMID 39737184, 2024). "Furthermore we evaluated the gene expression of KIT as well as the alternative RTK FLT3, CSF1-R, PDGFRB, AXL and MET in mutated and non-mutated gastrointestinal stromal tumors by qPCR using the identified reference genes." (PMID 21171987, 2010).
liver fibrosis (73 papers, 2008 to 2026). "The diagnostic performance of PDGFRβ as well as PDGFRβ + FIB-4 in prediction of significant liver fibrosis in diabetic MAFLD patients was assessed." (PMID 40676525, 2025). "In TGF‐β1‐treated HLOs, receptor‐ligand expression was observed involving PDGFB and PDGFRB, recapitulating an important hallmark of liver fibrosis in vivo." (PMID 37962490, 2023). "A recent study showed the diagnostic value of soluble PDGFRβ levels in liver fibrosis independently of the etiology of liver disease." (PMID 37733133, 2023). "PDGFRβ has not only been identified as a marker of hepatic stellate cell activation and associated liver fibrosis, but has also been found to be elevated in HCC tissue, therefore suggesting its ability to mark both cirrhosis and HCC." (PMID 34362181, 2021). "We previously reported the diagnostic utility of circulating PDGFRβ protein levels to detect significant liver fibrosis." (PMID 31470644, 2019). "Moreover, the direct targeting of PDGF receptor beta (PDGFRB) by miR-26b-5p was associated with the negative regulation of angiogenesis and fibrosis in a liver fibrosis model treated with methionine-choline-deficient and high-fat diets." (PMID 31653075, 2019). "Thus, curcumin binding to Lys163 of PDGFRB may inhibit the formation of this PDGF-PDGFRB complex, which signaling enhancement represents a hallmark in the development of liver fibrosis." (PMID 36319750, 2022). "As we recently reported the highly discriminative potential of circulating PDGFRβ-levels for significant liver fibrosis in patients with various aetiologies of liver disease, we generated a second diagnostic algorithm combining the miRFIB-score with such circulating PDGFRβ-levels, the miRFIBp-score." (PMID 31470644, 2019). "We enrolled 90 MAFLD patients (50 diabetic and 40 non-diabetic) as well as 40 healthy controls to assess the utility of PDGFRβ as a non-invasive biomarker for prediction of liver fibrosis in diabetic MAFLD patients." (PMID 40676525, 2025). "In liver fibrosis, both PDGFRα and PDGFRβ are upregulated, with PDGFRα expressed in liver progenitor cells and PDGFRβ mainly expressed in HSCs." (PMID 40393967, 2025). "Univariate logistic regression analysis revealed that factors predicting significant liver fibrosis (≥ F2) in the diabetic MAFLD group were PDGFRβ, smoking, visceral fat, and FIB-4 score (p = < 0.001, 0.047, 0.015, and 0.012, respectively)." (PMID 40676525, 2025). "A division of MAFLD subjects based on T2DM identified a strong discriminative ability of PDGFRβ for significant liver fibrosis." (PMID 40676525, 2025). "Treatment options for the management of individuals with MAFLD can lead to resolution of hepatic fibrosis, during which hepatic stellate cells undergo apoptosis, become senescent, or revert to an inactive state with diminished PDGFRβ production." (PMID 40676525, 2025). "PDGFRβ was the only independent predictor of significant liver fibrosis in diabetic MAFLD (p = 0.006)." (PMID 40676525, 2025). "PDGFRβ proved efficacy as a noninvasive biomarker in the prediction of significant liver fibrosis (≥ F2) in diabetic MAFLD patients." (PMID 40676525, 2025). "Mechanistically, TINAGL1 directly binds to and stabilizes PDGF-BB, leading to activation of HSCs and triggering liver fibrosis through the PDGF-BB/PDGFRβ signaling pathway." (PMID 39781468, 2025). "[68Ga]Ga-DOTA-Cys-ATH001 was evaluated for binding sections of human frozen liver biopsies from individuals with variable amount of hepatic fibrosis, as well as PDGFRβ positive sectioned U87 cells as positive controls." (PMID 41389114, 2025). "This work fills this gap by demonstrating that PDGFRβ more accurately predicts severe liver fibrosis in diabetic MAFLD patients, especially when combined with the FIB-4 score." (PMID 40676525, 2025). "The sensitivity, specificity, PPV, and NPV of PDGFRβ to predict significant liver fibrosis in diabetic MAFLD patients were 85%, 93.33%, 89.5%, and 90.3%, respectively, at a cutoff > 2.54." (PMID 40676525, 2025).